JAK2 (Janus kinase 2)
Diseases named in the same sentence as JAK2 in open-access papers (continued):
Sharing a sentence is not in itself a finding about the gene and the disease.
lung cancer (continued). "Besides JAK2/STAT3 signaling, we also demonstrate that SH2B3 interacts with SHP2 to inhibit the SHP2/Grb2/PI3K/AKT signaling pathway in lung cancer cells." (PMID 35589677, 2022). "Moreover, we show that SH2B3 binds to JAK2 to inhibit JAK2/STAT3 signaling, supporting that hyperactivity of JAK2/STAT3 signaling in lung cancer cells results from diminished SH2B3 expression level." (PMID 35589677, 2022). "SH2B3 inhibits JAK2/STAT3 and PI3K/AKT signaling pathways to induce anoikis in lung cancer." (PMID 36230714, 2022). "Because EML4-ALK interacted with the JAK2-STAT pathway resulting in the phosphorylation of STAT proteins in EML4-ALK-positive lung cancer cells, we investigated whether IL4 or IL6 activated the JAK2-STAT pathway in these cells." (PMID 34090412, 2021). "The lung cancer stemness and CSC features can be mediated via JAK2/STAT3 axis." (PMID 34769099, 2021). "Blocking the JAK2/STAT3 signaling pathway in non-small cell carcinoma (NSCLC) inhibits the proliferation, angiogenesis, invasion, and migration ability of NSCLC and additionally inhibits the development of lung cancer." (PMID 34900727, 2021). "Furthermore, it is increasingly evident that the JAK2/STAT3 signaling pathway plays a critical role in tumor growth, proliferation, and metastasis of several malignancies, including lung cancer." (PMID 31492006, 2019). "Furthermore, it is increasingly evident that the JAK2/STAT3 signaling pathway plays a critical role in tumor growth, proliferation, and the metastasis of several malignancies, including lung cancer." (PMID 31492006, 2019). "Because LDOC1 is a regulator of the IL-6/JAK2/STAT3 axis, LDOC1 may play different roles during different stages of lung cancer." (PMID 30634502, 2019). "Additionally, the inhibition of IL-6/STAT3 signaling pathway by IL-6 neutralizing antibody or specific inhibitors of JAK2/STAT3 reversed CAF-CM induced EMT and migration of lung cancer cells." (PMID 29100297, 2017). "In addition, PD-L1 expression of the PD-L1-amplified lung cancer cell line, HCC4006, is shown to be reduced by JAK2-specific and STAT3-specific inhibitors." (PMID 27050074, 2016). "Whereas it was found STAT3 acted as a JAK1/JAK2-induced oncogenic driver in lung cancers, STAT1 expression was reported to form part of a genetic signature predicting event-free and overall survival of lung cancer patients." (PMID 24833526, 2014). "In lung cancers JAK1 and JAK2 induce oncogenic signaling through STAT3." (PMID 24833526, 2014). "It has also been found to reduce JAK2/STAT3 signaling and induce autophagy through the production of ROS in SKOV3/DDP ovarian tumor cells resistant to cisplatin 29, as well as suppressing the growth of lung cancer by blocking β-catenin induction of the epithelial-mesenchymal transition." (PMID 39513117, 2024). "Therefore, we put forward the speculation that the knockdown of metastasis-related protein BRD4 could mediate the JAK2/STAT3 pathway and suppress the lung cancer cell migration and invasion." (PMID 31621555, 2020). "Moreover, PEITC anti-metastatic potential reported to be significantly increased after inhibition of autophagy and, subsequently, inactivation of the JAK2 (Janus kinase 2)/STAT3 (signal transducer and activator of transcription 3) pathway in three lung cancer cell lines." (PMID 31003534, 2019). "In addition, we have provided strong evidence that the JAK2/STAT3/C/EBPβ-induced IL-6 positive feedback pathway is important for lung cancer cell growth, migration, and invasion, which suggests that the STAT3-C/EBPβ-IL-6 signaling axis plays a crucial role in TAM-mediated lung cancer progression." (PMID 38424624, 2024). "Of these fusions, 16 (including ALK, ARAF, BRAF, FGFR1, FGFR3, RET, and ROS1) and 21 (including ABL1, GNAS, JAK2, and NRG1) were classified as either related to lung cancer, or as oncogenes that have not been reported in lung cancer, respectively." (PMID 36153311, 2022).
lung cancer (continued). "JAK2 is a major upstream nonreceptor tyrosine kinase that activates STAT3 and we investigated the effect of CHK9 on the activation of JAK2 in lung cancer cells." (PMID 32967366, 2020). "We found that even though prostate cancer cells CWR22Rv-1 and lung cancer cells NCI-H1299 displayed JAK2/STAT3 expression and activating phosphorylation, Cuc IIa still induced apoptosis without clearly inhibiting JAK2/STAT3 phosphorylation." (PMID 21304528, 2011). "However, our immunoblotting analysis showed that the expression of JAK1, JAK2 and PKC was not significantly altered when HDAC7 expression was depleted in human lung cancer cell line H1299." (PMID 29126425, 2017).
primary myelofibrosis (154 papers, 2010 to 2026). Myelofibrosis with myeloid metaplasia is a myeloproliferative disease with annual incidence of approximately 1 case per 100,000 individuals and age at diagnosis around 60 (an increased prevalence is noted in Ashkenazi Jews). "HDACis have been tested in combination with ruxolitinib, resulting in a decrease in spleen volume, improvement in bone marrow fibrosis, and a decrease in JAK2 V617F allele load." (PMID 40699626, 2025). "Primary myelofibrosis (PMF) is a clonal blood disorder characterized by mutually exclusive driver mutations in JAK2, CALR, or MPL genes." (PMID 40319310, 2025). "In particular, the V617F JAK2 mutation, which is found in most patients with polycythemia vera, essential thrombocythemia, and idiopathic myelofibrosis, makes this kinase a potential therapeutic target to treat patients suffering from these types of cancer." (PMID 39339202, 2024). "Other than overproduction of blood cells, the JAK2 mutation can also lead to bone marrow fibrosis, splenomegaly and increased clotting risk potentially causing deep vein thrombosis, pulmonary embolism, heart attack, and stroke." (PMID 39877786, 2024). "In fact, patients with primary myelofibrosis who have the same mutation have a significantly longer overall survival rate compared to subjects positive for other mutations (JAK2, V617F, or MPL)." (PMID 38673505, 2024). "A role of endothelial cells (ECs) in Primary Myelofibrosis (PMF) was supposed since JAK2 mutation was found in endothelial precursor cells (EPCs) and in ECs captured by laser microdissection." (PMID 34685741, 2021). "Seven patients were recognized as primary myelofibrosis and exhibited JAK2 V617F mutation in 57.1%, CALR type 1 in 14.3 %, CALR type 2 in 14.3% and no mutation in 14.3%." (PMID 33936230, 2021). "Still, seven (47%) patients experienced at least one-grade improvement in bone marrow fibrosis, though little change was noted in JAK2 V617F mutant allele fraction." (PMID 32823910, 2020). "The patient was diagnosed with CVT and multiple intracranial hemorrhage caused by JAK2 V617F mutation-positive primary myelofibrosis by neuroimage and whole-exome sequencing." (PMID 32846801, 2020). "Primary myelofibrosis is a condition associated with somaticmutations in JAK2 or other factors that activate the thrombopoietin signalingpathway." (PMID 32303876, 2020). "In contrast, JAK2 mutations are present in essential thrombocythaemia (ET) and primary myelofibrosis (PMF) in only 50–60%." (PMID 26202929, 2016). "The JAK2 V617F mutation, associated with primary myeloproliferative disorders, is present in up to one half of the patients with primary myelofibrosis." (PMID 25045617, 2014). "The authors also described a family with three affected members, in which they found the JAK2 V617F mutation in a primary myelofibrosis (PMF) patient and the MPL W515L in an ET patient." (PMID 25525531, 2014). "The influence of JAK2 V617F mutation on blast transformation (BT) and overall survival (OS) in primary myelofibrosis (PMF) is controversial." (PMID 23555782, 2013). "The somatically acquired Janus Kinase 2 (JAK2) mutation (V617F) is borne by approximately 60% of patients with primary myelofibrosis (PMF)." (PMID 23555782, 2013). "Patients with intermediate-2 or high-risk primary myelofibrosis (PMF) on JAK2 inhibitors could have a worse outcome if they become infected with the virus; however, the effect of JAK inhibitors increasing of SARS-Cov-2 infection is unknown." (PMID 33791197, 2021). "Beyond an impact on spleen size and disease-related symptoms, ruxolitinib has shown favorable impact on nutritional parameters and hepatomegaly, while its impact on JAK2 allele burden and bone marrow fibrosis has been modest, with more significant potential impact emerging with long-term treatment." (PMID 32823910, 2020).
primary myelofibrosis (continued). "In addition to this, and consistent with other reports, some patients experienced reductions in JAK2 V617F allele burden, and a notable proportion of patients (48%) maintained or had improvement in their bone marrow fibrosis with longer-term ruxolitinib use." (PMID 27211272, 2016). "Despite this, the JAK2 V617F mutation may still be valuable in the diagnosis of MPN; for example, a previous study indicated that JAK2 V617F allele evaluation may be used to discriminate MDS from MPN in specimens with bone marrow fibrosis." (PMID 25624900, 2015). "Based on bone marrow morphology, biopsy (revealing Grade MF-2 fibrosis), and molecular testing (detecting a JAK2 V617F mutation with a variant allele frequency of 44.67% and an ASXL1 mutation), a diagnosis of primary myelofibrosis (PMF) was established." (PMID 41988126, 2026). "Ruxolitinib is a potent JAK1/JAK2 inhibitor, approved for the treatment of primary myelofibrosis (PMF) patients based on the concept of inhibition of oncogenic signaling." (PMID 40413183, 2025). "Samples from 200 consecutive MPN patients (71 ET, 46 primary myelofibrosis (PMF), 83 PV) were analyzed for the presence of JAK2-R1063H variant." (PMID 40841769, 2025). "Among them, ruxolitinib was the first JAK2 inhibitor approved for its use in humans to treat primary myelofibrosis." (PMID 39339202, 2024). "Three patients were diagnosed with primary myelofibrosis (PMF), all of whom harbored the JAK2 V617F mutation." (PMID 38496121, 2024). "Recent advances in the diagnostics of CRTfs-specific MPNs relate to primary myelofibrosis (PMF) and ET, which lack mutations in JAK2 and MPL." (PMID 35743246, 2022). "Somatic variants in JAK2 and SH2B3 genes are the cause for somatic erythrocytosis (OMIM ID: 133100), somatic myelofibrosis (OMIM ID: 254450), and thrombocythemia (OMIM ID: 614521, 187950)." (PMID 34349782, 2021). "In the patients with concurrent grade ≥2 fibrosis (n = 7) JAK2 V617F analyses were performed to exclude primary myelofibrosis (PMF)." (PMID 33799933, 2021). "More specifically, one patient was diagnosed with PV, one patient with post-ET MF, two patients with primary myelofibrosis (PMF), and the remaining two with pre-fibrotic PMF; all of them were positive for the mutation JAK2 V617F." (PMID 31781224, 2019). "Recently, calreticulin (CALR) mutations were discovered in ~30% JAK2/MPL-unmutated ET and primary myelofibrosis." (PMID 28415571, 2017). "Gene mutations in epigenetic regulators (ASXL1, TET2, DNMT3A and EZH2) and RNA splicing (U2AF1 and SRSF2) were considered as the additional subclonal mutations and cooperated with the MPN driver mutation (JAK2, MPL or CALR) to play a key role in the pathogenesis of primary myelofibrosis." (PMID 35740649, 2022). "To test this, we employed a JAK2 V617F transgenic mouse model, which mirrors PV natural history, with erythrocytosis, granulocytosis, thrombocytosis, splenomegaly and eventually anemia and osteomyelofibrosis." (PMID 33777803, 2021). "In MPN JAK2 or MPL mutation are not linked to the propensity for bone marrow fibrosis." (PMID 23259436, 2012). "This study aimed to identify effective targets for carcinogenesis of primary myelofibrosis (PMF), as well as to screen ideal lead compounds with potential inhibition effect on Janus kinase 2 to contribute to the medication design and development." (PMID 33686952, 2021). "Unexpectedly, the PV phenotype was modified; this involved both the reversal of splenomegaly and osteomyelofibrosis, and a reduction in marrow HSC, despite the biallelic expression of functional MPL expressing JAK2 V617F." (PMID 33777803, 2021). "Primary myelofibrosis is a Ph-negative chronic myeloproliferative neoplasm characterized by bone marrow fibrosis and associated with the involvement of several pathways, in addition to bone marrow microenvironment alterations, mostly driven by the activation of the cytokine receptor/JAK2 pathway." (PMID 34905501, 2021).
primary myelofibrosis (continued). "A bone marrow aspirate showed no infiltration of Langerhans cells, but alterations consistent with primary myelofibrosis (PMF) and a polymerase chain reaction test were positive for JAK2 V617F." (PMID 33953993, 2021). "Bone marrow biopsy initially demonstrated significant fibrosis concerning for primary myelofibrosis, though JAK2 testing was negative." (PMID 41235128, 2025). "While ruxolitinib is targeted for primary myelofibrosis (PMF) and its mechanism does not specifically target the JAK2 V617F mutation, it achieves significant splenic reduction and symptom relief by attenuating the activity of the JAK-STAT pathways." (PMID 39224801, 2024). "This is also important because JAK2 inhibition, as a therapeutic modality for MPNs, does not greatly or reliably reduce the malignant clonal burden or extent of bone marrow fibrosis." (PMID 34140953, 2021). "However, the patient did not have typical symptoms of primary myelofibrosis (PMF; such as splenomegaly, tear-drop erythrocytes), and previous genetic testing results did not identify PMF-related gene mutations such as JAK2, CALR, MPL." (PMID 40740952, 2025). "The patient has no JAK2 (Janus kinase 2, V617 F), MPL (thrombopoietin receptor, W515 K/L) and CALR (calreticulin, exon 9 indel) mutation which are identified in approximately 90% of patients to help with the diagnosis and the prognostic stratification of Primary myelofibrosis (PMF) patients." (PMID 32772769, 2020).
thrombosis (130 papers, 2011 to 2026). "Croatian hematologists also recommend aspirin to 90.3%, 67.7%, 61.3%, and 48.4% of MF patients with cardiovascular risk factors, prior thrombosis, JAK2-mutated MF, and post-PV MF, respectively." (PMID 40094998, 2025). "Patients older than 60 years of age or with a history of thrombosis are considered at high risk for thrombosis, and platelet activation is enhanced and the risk of thrombus formation is increased, especially in patients with ET with JAK 2 mutations." (PMID 40381108, 2025). "Low‐dose aspirin (typically 75 mg/day) is recommended for all patients with JAK2 mutated ET to reduce arterial thrombosis risk, with a twice‐daily schedule generally reserved for those with problematic microvascular symptoms." (PMID 40625825, 2025). "This aligns with reports indicating that previous history of thrombosis, older age, and JAK2 mutations together significantly heighten thrombotic risk." (PMID 40231292, 2025). "JAK2-V617F mutation was associated with an increased risk of venous thrombosis (OR 2.6, 95% CI 1.01–7.16)." (PMID 41153823, 2025). "The high-risk group consists of patients with a history of thrombosis or those aged over 60 years with a JAK2 mutation." (PMID 40507313, 2025). "Research shows that CALR-mutated patients, despite often presenting with higher platelet counts, have a lower risk of thrombosis than JAK2-mutated patients." (PMID 40231292, 2025). "The patient was classified as having ET with a high risk of both thrombosis and a poor prognosis because of his age, history of thrombosis, elevated white blood cell count, and JAK2 mutation." (PMID 39897264, 2025). "PMF patients harboring JAK2 mutations often exhibit higher leukocyte counts and hemoglobin levels and are more prone to thrombosis." (PMID 39395952, 2024). "Current drug therapy has not been shown to modify the natural history of the disease, and its use is primarily directed at the prevention of thrombosis, guided by thrombosis risk models that are based on thrombosis history, age, and presence of JAK2 mutation." (PMID 38238303, 2024). "The primary risk factors for stroke in PV patients are age, JAK2 exon V617F mutation (JAK2/V617F), as well as previous history of thrombosis, and early diagnosis can improve the management and clinical outcomes of patients." (PMID 38363912, 2024). "Concerning venous thrombosis at or prior to diagnosis, the presence of JAK2 mutation was the only significant risk factor identified (p = 0.02)." (PMID 38238287, 2024). "Due to the significant association of TLR2 levels with Jak2 mutation and leukocytosis, which were reported to be associated with a higher incidence of thrombosis in MPN, studies were conducted to investigate platelet activation correlated with TLR2 levels." (PMID 39157201, 2024). "It categorizes patients into four risk groups based on three factors: age, presence of JAK-2 mutations, and history of thrombosis." (PMID 38606222, 2024). "Among PV patients, the factors of age, positive JAK2/V617F mutations, and previous thrombosis events are the main risk factors for stroke." (PMID 38363912, 2024). "Arterial and venous thrombosis rates were significantly lower in CALR-mutated cases when compared with JAK2, whose thrombosis risk was otherwise similar to those with MPL mutation and TN (p < 0.01 and <0.01)." (PMID 38238303, 2024). "Incidence rates of major arterial/venous thrombosis for JAK2, type 1/1-like CALR, type 2/2-like CALR, MPL-mutated and TN cases were 10%/8%, 10%/5%, 8%/4%, 14%/9% and 3%/2%, respectively." (PMID 38238287, 2024). "The IPSET thrombosis model was developed to estimate thrombotic risk in newly diagnosed patients with ET based on age, previous thrombosis, cardiovascular risk factors and JAK2-V617F status." (PMID 37958701, 2023). "A positive correlation was found between thrombosis, JAK2 mutation (p = 0.006), and MMP9 polymorphism (p = 0.002) in the ET group." (PMID 36611455, 2023).